RNU2-8P (RNA, U2 small nuclear 8, pseudogene)
Gene: Small nuclear RNA gene on chromosome 6 (121,580,332 to 121,580,521, reverse strand). Ensembl gene ENSG00000222659.
Homologues: Orthologues: chimpanzee U2 (99% identical), macaque U2 (93% identical), macaque U2 (91% identical). Paralogues in human: RNU2-59P (84% identical), RNU2-48P (83% identical), RNU2-3P (83% identical), U2 (82% identical), U2 (81% identical), RNU2-15P (80% identical), RNU2-2 (79% identical), RNU2-6P (79% identical), RNU2-23P (79% identical), RNU2-33P (79% identical), RNU2-14P (78% identical), RNU2-4P (78% identical), and 66 more.